MT3 (metallothionein 3)
Diseases named in the same sentence as MT3 in open-access papers (continued):
Sharing a sentence is not in itself a finding about the gene and the disease.
cancer (26 papers, 2005 to 2025). A tumor composed of atypical neoplastic, often pleomorphic cells that invade other tissues. "We have shown that the MT3 promoter has a heterogeneous pattern of methylation in oeosphageal cancer cell lines, and is associated with a reduction in the gene expression." (PMID 16351731, 2005). "Interestingly, the analysis of a comparative toxicogenomics database indicated that MT3 is regarded as the cancer-associated arsenic-interacting gene in the bladder." (PMID 30813460, 2019). "Indeed, in the present study, we found that acquired chemoresistance to CDDP is associated with pronounced up-regulation of MT-3, which has an increasing significance as a diagnostic marker of various cancers and its presence frequently correlates with the poor chemotherapy outcome." (PMID 30871063, 2019). "In MCF-7 cells, a breast cancer cell line, the C- and N-terminal of MT3 contributed to the growth inhibition of cancer cells." (PMID 32843100, 2020). "MT-3 shows a brain-specific expression, mainly in glutamatergic neurons; however, up-regulation of these proteins has also been found in a number of cancers, where its presence positively correlates with the poor survival prognosis." (PMID 29435113, 2018). "Although MT-3 expression has been identified in cancer cells, its exact role in oncological diseases requires further clarification." (PMID 25015776, 2015). "Although numerous studies have been performed on the role of MT-1/2 isoforms in various normal and pathological processes, little is known yet regarding the role of metallothionein-3 (MT-3) in cancer cells." (PMID 25015776, 2015). "The unexpected variable methylation levels in the MT3 promoter CpG island highlight the critical importance of selecting the proper promoter sites for DNA methylation studies in cancer." (PMID 21818286, 2011). "The MTT and clonogenic assays results could shed some light on the MT-3 involved in inducing resistance to CDDP in cancer cells." (PMID 29435113, 2018). "Taken together, the role of MT3 in cancer progression remains ambiguous and inconsistent." (PMID 25933064, 2015). "However, the exact role of MT3 in cancer cells remains controversial." (PMID 36133439, 2022). "In another sense, MT3‐MMP might play a role in inhibition of ESCC cancer cells." (PMID 27292876, 2016). "Cancer cells can also deploy MT1-MMP, as well as membrane-anchored MMPs, MT2-MMP and MT3-MMP, to remodel basement membranes during trafficking." (PMID 36302921, 2022). "The hub genes identified by PPI network analysis include SYN1, CNTN2, FAIM2, MT3, and SH3GL2, which are involved in the pathogenesis of different cancers." (PMID 32328342, 2020). "For example, MT3‐MMP can activate pro‐MMP‐2 9, while MMP‐2 is known to promote cancer cell invasiveness." (PMID 27292876, 2016). "AK cases exhibit an intermediate MT-3 expression, which is higher in comparison to that noted in normal skin epidermis, but lower when compared to that of SCC cancer cells." (PMID 25015776, 2015). "In brief, DUSP1, ZFP36, SLC2A3, HMGB1, STAT3, MT3, and ALOX5 were all FRGs that might be involved in cancer development and immune regulation." (PMID 36131791, 2022). "Although, we did not notice any correlations between MT-3 expression intensity in cancer cells and SCC patients clinico-pathological data, the prognostic impact of MT-3 expression remains to be yet determined." (PMID 25015776, 2015). "Metallothionein III (MT3) overexpression contributes to carcinogenesis and poor prognosis of several other types of cancer patients but not clearly for HCC patients." (PMID 35705729, 2022).
neurodegenerative disease (8 papers, 2010 to 2025). A disorder of the central nervous system characterized by gradual and progressive loss of neural tissue and neurologic function. "S100a6, which is upregulated with Mt3, expressed a calcium- and zinc-binding protein that has been associated with misregulation of zinc levels in several neurodegenerative diseases." (PMID 28587098, 2017). "Cluster 2 exhibits prominent upregulation of metallothionein 1 and 3 (Mt1 and Mt3), which have been identified to be protective in the context of neurodegenerative disease and CNS insult." (PMID 40948563, 2025). "As an inhibitor of neuronal growth, MT3 is also expected to play an important role in various neurodegenerative disease." (PMID 32843100, 2020). "Therefore, it is necessary to study the mechanism of action of MT3 on diverse neurodegenerative diseases." (PMID 32843100, 2020). "Collectively, we speculate that Cu physiologically accumulating and binding to MT-3 in neural cells is one of contributors to the pathogenesis of neurodegenerative diseases, by acting as a pro-oxidant." (PMID 27623342, 2016). "The potential role of MT3 in the progression of neurodegenerative diseases still raises some controversies; while according to some authors MT3 acts as a protective factor against neurodegenerative diseases, others showed that it may stimulate progression thereof." (PMID 27551319, 2016). "Therefore, although it has not been fully identified and need to be further studied, MT3-induced control of cytoskeletal filaments may in part contribute to severe neurodegenerative diseases." (PMID 32843100, 2020).
infection (5 papers, 2006 to 2025). The state of being infected such as from the introduction of a foreign agent such as serum, vaccine, antigenic substance or organism. "WT and Mt3-/- mice were treated i.p. with MCC950 (NLRP3 inhibitor) followed by infection i.p. with E. coli." (PMID 34867993, 2021). "We infected WT, Casp-11-/-, Mt3-/-, and Mt3-/-Casp-11-/- mice i.p. with E. coli and assessed bacterial burden 6h post-infection." (PMID 34867993, 2021). "In the context of gram-negative bacterial pathogenesis, our data indicate that strategies aimed at combined targeting of MT3 and the caspase-11 inflammasome may be more beneficial in infection control than targeting caspase-11 alone." (PMID 34867993, 2021). "As an intracellular factor which regulates the differentiation of osteoblastic cells, it will be interesting for future studies to analyze the role of MT3 on osteoblasts in infection conditions, which could further identify the potential clinical advantages of MT3." (PMID 33919218, 2021). "Some of the highly expressed genes (Log2 FC > 3.5) in inverse manner during Neisseria and Borrelia like HAPLN1, MT3, PITX2, ID4, ELAFIN, SLPI, etc., could be targeted to know their relevance in favoring or resisting the infection." (PMID 38179419, 2023). "The presence of mt3 in the TM4 Tmp clearly facilitates infection of cells in stationary phase, and it would not be surprising if this provides a selective advantage to phage propagation in natural environments." (PMID 17083467, 2006).
neurological diseases (4 papers, 2010 to 2023). "Metallothionein-3 is a component of a multiprotein complex which very early on was associated with neurological disorders in humans." (PMID 25925689, 2015). "In addition, MT3 germline knockout (KO) mice have been evaluated in the field of the neurological disorders, and have impaired social interactions but normal spontaneous motor activity, habituation, learning and memory." (PMID 38040717, 2023). "In light of evidence that autophagy and lysosomes may play significant roles in the pathogenesis of various neurological diseases, further insight into the contribution of zinc dynamics and metallothionein-3 function may help provide ways to effectively regulate these processes in brain cells." (PMID 20974010, 2010).
bacterial infection (1 paper, 2021). "Collectively, these data demonstrate that MT3 negatively controls activation of the non-canonical inflammasome and that both MT3 and caspase-11 cripple resistance to bacterial infection." (PMID 34867993, 2021).
bone disorder (1 paper, 2024). "The present study demonstrated that MT3 elevation is a potential therapeutic strategy for osteolytic bone disorders, and it established for the first time that MT3 is a crucial bone mass regulator." (PMID 39085359, 2024).
MT3 also shares sentences with these, for which no sentence is quoted: Cerebral ischemia (4 papers); memory impairment (2); retinal degeneration (2); schizophrenia (2); actinic keratosis (1); adenoma (1); Alexander disease (1); astrocytic tumor (1); autism (1); basal cell carcinoma (1); brain diseases (1); cardiomyopathy (1); cognitive decline (1); colon (1); diabetic retinopathy (1); Down syndrome (1); encephalomyelitis (1); entropion (1); fungal infections (1); glaucoma (1); heart failure (1); Hepatic steatosis (1); insomnia (1); ischemia (1); liver cancer (1); lung carcinoma (1); medulloblastoma (1); metastatic melanoma (1); multiple sclerosis (1); multiple system atrophy (1).
A further 9 diseases each share a sentence with MT3 in 1 paper.